NCOA3 (nuclear receptor coactivator 3)
Diseases named in the same sentence as NCOA3 in open-access papers (continued):
Sharing a sentence is not in itself a finding about the gene and the disease.
cancer (continued). "First, the NCOA3-p300-NF-κB complex-mediated regulation may exist in all ER-positive cells (either normal cells or cancer cells)." (PMID 36853387, 2023). "NCOA3 is a well-studied oncogene that is up-regulated in many cancers." (PMID 36702236, 2023). "Furthermore, the expression of ENO1 and other glycolysis genes also can be regulated by sineoculis homeobox homolog 1 (SIX1), which interact with acetyltransferase 1 (HBO1) and Nuclear receptor coactivator 3 (AIB1) to affect Warburg effect in cancer." (PMID 34671213, 2021). "Accumulating evidence shows that NCOA3 is highly expressed in a various human cancers, and it can interact with nuclear receptors and other transcription factors to regulate the expression of their target genes involved in many signaling pathways, including EGFR, Akt, MAPK, E2F1, and Notch." (PMID 29360267, 2018). "Notably, NCOA3 negatively correlated with the two miRNA was clearly upregulated in taxol-sensitive brest cancer tissues compared with normal tissues." (PMID 27831559, 2016). "Furthermore, SRC-3delta4, a splicing variant of NCOA3, can bridge EGFR to phosphorylate and activate FAK, which potentiates cancer cell survival, proliferation, migration and invasion." (PMID 26287601, 2015). "PELP1 interacts with AIB1 (NCOA3)-containing complexes, and such interactions are shown to promote advanced cancer phenotypes." (PMID 41463382, 2025). "The genes selected using this method included NCOA3, HOXA1, FOLR1, SOCS1, and PIK4CA, which showed similar expression patterns related to survival in patients with cancer." (PMID 29854877, 2018). "In terms of the genes that are exclusively affected by tumor-specific somatic TE insertions, we also observed the enrichment of affected genes in the cancer pathway (due to tumor-specific TE insertions in genes such as COL4A6, PLCB4, ARNT2, LRP5, NCOA3, and CTNNA2)." (PMID 35013466, 2022). "Here, we prove the feasibility of assigning genes to cancer pathways by genome-wide forward genetics using genome-edited human cell systems, link FOXO3, NCOA3, and TCF7L2 to phenotypes of the EGFR/Ras/MAPK pathway, and implicate FOXO3 and NCOA3 in the response to anti-EGFR therapy." (PMID 29301589, 2018). "These three genes (i.e. FOXO3, NCOA3, and TCF7L2) also play roles in other human cancers." (PMID 29301589, 2018).
tumor (133 papers, 2004 to 2025). "We also evaluated the antitumor effects of knockdown of NCOA3-p300-NF-κB components by establishing a tumor xenograft model by injecting Control-KD1, RelA-KD1, NFKB1-KD1, p300-KD1, or NCOA3-KD1 cells (T47D background) into nude mice." (PMID 36853387, 2023). "Cyclin D1 enhances the activity of Erα by interacting with its co-regulators, SRC1 (NCOA1) and AIB1 (NCOA3), in tumor cells." (PMID 37427143, 2023). "We also evaluated the antitumor effects of NCOA3 inhibitors by establishing a tumor xenograft model by injecting T47D cells and then comparing mice with or without implanted 0.18 mg E2 pellets." (PMID 36853387, 2023). "Implantation of a 0.18 mg E2 pellet into mice injected with NCOA3-p300-NF-κB component-KD cells partially restored the inhibited tumor growth." (PMID 36853387, 2023). "Collectively, these cellular experiments supported the inhibitory role of MAD2L2 in CRC development and suggested that MAD2L2 functioned as a tumor suppressor in CRC through the down‐regulation of NCOA3." (PMID 29360267, 2018). "Increased expression of NCOA3 and NCOA1 has been reported in prostate cancers, and their high expression level is associated with tumour grade and disease recurrence." (PMID 29545931, 2018). "Copy number alterations of MYC (8q24.21), FHIT (3p14.2), WDR60 (7q36.3), COL4A2 (13q34), NFATC1 (18q23), and NCOA3 (20q12) were analyzed in six matched tumor and normal tissue pairs (268–1, 271–1, 272–2, 301–1, 685–1 and 685–2)." (PMID 26360582, 2015). "Other HATs such as the human homolog of males absent on the first (hMOF/KAT8) as well as the Steroid Receptor Coactivators-1 and -3 (SRC1/NCOA1 and SRC3/NCOA3) have been shown to play tumor and metastasis suppressor and activator roles, respectively." (PMID 24840099, 2014). "Notably, several target genes—including WNK1, CDK6, NCOA3, and NFAT5—are functionally linked to key oncogenic processes such as tumor growth, proliferation, and metastasis (eFigure 7A in Supplement 1)." (PMID 40737022, 2025). "NCOA3 is known to have a positive effect on tumor cell growth." (PMID 36702236, 2023). "We also examined the mRNA levels of NCOA3 in human ER-negative and ER-positive tumor samples." (PMID 36853387, 2023). "Furthermore, NCOA3 knockdown slowed human tumor xenograft growth in mice and NCOA3 enforced expression increased tumor growth." (PMID 34768683, 2021). "Moreover, NCOA3 is positively correlated with TERT expression in HCC tumor tissues, and high expression of both NCOA3 and TERT predicts a poor prognosis in HCC patients." (PMID 33239622, 2020). "Moreover, consistent with previous studies, the expression of NCOA3 was significantly increased in all primary tumors analyzed (i.e., taxol-resistant and taxol-sensitive tumor tissues) relative to their adjacent normal tissues." (PMID 27831559, 2016). "The functional relationship between PLAC1 and NCOA3 as well as the correlation analysis of PLAC1 expression with various clinical parameters like tumor size, overall and disease-free survival as well as resistance to therapy will be subjects of further studies." (PMID 24304549, 2013). "Thus, cytosolic NCOA3 may promote tumor progression by downregulating PTEN activity for PIP3-mediated macropinocytosis and thereby ALB uptake and energetics during cell migration." (PMID 40186033, 2025). "Furthermore, liver tissue from patients with HCC showed increased TM4SF5 expression linked to increased cytosolic staining of NCOA3 in tumor lesions but not in nontumor regions." (PMID 40186033, 2025). "The stabilization of NCOA3 by HBx promotes the activation of NF-κB signaling and the expression of MMP-9, a key factor in tumor invasion." (PMID 40332052, 2025). "Increases the expression of NCOA3 and CLU, which subsequently decreases metastasis and tumor growth." (PMID 36207986, 2023). "NCOA3 promotes HCC cell growth and tumor progression in vitro and in vivo through upregulating the TERT signaling." (PMID 33239622, 2020).
tumor (continued). "We then detected the NCOA3 and TERT protein expression in the tumor and peritumoral tissues of 30 HCC patients from the Sun Yat-Sen University Cancer Center." (PMID 33239622, 2020). "In this study, we found that NCOA3 had higher expression in HCC cells than in the LO2 immortalized hepatocytes, and in HCC tumor tissues than in peritumoral tissues." (PMID 33239622, 2020). "Here, we have identified nuclear receptor coactivator-3 (NCOA3) as a new modulator of TERT expression and tumor growth in HCC." (PMID 33239622, 2020). "Our results showed that both NCOA3 and TERT had higher expression in the tumor tissues, and the expression of NCOA3 and TERT were, respectively, elevated in 88% (26/30) and 78% (23/30) of the HCC tissues." (PMID 33239622, 2020). "Our study has discovered a novel role of MAD2L2 in regulating the degradation of NCOA3 and suggested that MAD2L2 functions as a tumor suppressor in CRC." (PMID 29360267, 2018). "We have discovered a novel role of MAD2L2 in the regulation of NCOA3 degradation and proposed that MAD2L2 serves as a tumor suppressor in CRC." (PMID 29360267, 2018). "Among the tumor-related genes, the top amplified genes included ERBB2 (17q21), MYC (8q24), GNAS (20q13), EGFR (7p11), ZNF217 (20q13), CCNE1(19q12), NCOA3 (20q13), and CDK6 (7q21), and the most frequently deleted genes were CDKN2A (9p21), CDKN2B (9p21), KIT (4q12), SMAD4 (18q21), and FGFR1 (8p12)." (PMID 31541076, 2019). "This discloses that molecules targeting only “NCOA3” show no increase in potency to inhibit tumour cell growth." (PMID 24553133, 2014). "Depletion of the NCOA3-p300-NF-κB components or blockage of NCOA3 function with inhibitors (gossypol and bufalin) in ER-positive cells suppressed BCL2, BCL2A1, BCL2L2, and MCL1 expression, while also decreasing cell viability, colony formation, cell invasion, and tumor growth." (PMID 36853387, 2023). "Additionally, RNAseq did not identify differential expression of the AR or NCOA3 in canine OSA relative to non-tumor bone tissue." (PMID 32854182, 2020). "The present study used next generation RNA sequencing to identify novel differentially expressed genes in OSA tumor tissue as compared to matched non-tumor tissue and assessed NCOA3 and AR polyQ tract variations in affected and non-affected IWH and Rottweiler dogs." (PMID 32854182, 2020). "Tissue microarray data showed that the expression of NCOA3 and TERT were positively correlated in HCC patients (n = 53), and were higher in tumor tissues than in adjacent nontumor tissues." (PMID 33239622, 2020). "Among the five genes, analyses of the TCGA + GTXe44 datasets and GSE14520 patients with HCC showed that NCOA3 could be functionally related to TM4SF5 and positively higher in tumor tissues, unlike ALB levels." (PMID 40186033, 2025).
infection (4 papers, 2010 to 2025). The state of being infected such as from the introduction of a foreign agent such as serum, vaccine, antigenic substance or organism. "At last, we reduced miR-222-3p expression in colon tissue samples through the lentiviruses infection (P < .01), after which the expression of IGF2BP2 and NCOA3 was increased in the colon tissues (P < .01)." (PMID 40241612, 2025).
kidney diseases (1 paper, 2024). "In summary, we focus on the key role of the coactivator of NRs in podocyte homeostasis and DKD and provide new insights into the effect of NCOA3 in kidney diseases." (PMID 38483947, 2024).
metabolic disorders (1 paper, 2015). "However, to the best of our knowledge, studies on NCOA3 gene so far are carried out mainly on animal models, with no published epidemiologic studies that investigated the association of human NCOA3 single nucleotide polymorphisms (SNPs) and metabolic disorders." (PMID 26449542, 2015).
NCOA3 also shares sentences with these, for which no sentence is quoted: endometrial cancer (8 papers); multiple myeloma (8); bladder cancer (7); cervical carcinoma (6); B-cell lymphoma (5); cholangiocarcinoma (5); esophageal squamous cell carcinoma (5); metastatic tumors (5); non-small cell lung carcinoma (4); thyroid cancer (4); triple-negative breast carcinoma (4); autoimmune disease (3); colitis (3); endometriosis (3); glioma (3); invasive ductal carcinoma (3); lymph node metastasis (3); lymphoma (3); astrocytic tumor (2); blood cancer (2); bone cancer (2); chronic myeloid leukemia (2); dwarfism (2); esophageal cancer (2); Hepatic steatosis (2); mammary adenocarcinomas (2); mantle cell lymphoma (2); myocardial infarction (2); nasopharyngeal carcinoma (2); pancreatic adenocarcinoma (2).
A further 64 diseases each share a sentence with NCOA3 in 2 papers or fewer.